SPP1 (secreted phosphoprotein 1)
Diseases named in the same sentence as SPP1 in open-access papers (continued):
Sharing a sentence is not in itself a finding about the gene and the disease.
colon adenocarcinoma (7 papers, 2007 to 2024). "In both populations of patients with colon adenocarcinoma and rectum adenocarcinoma, higher SPP1 expression was correlated with shortened survival compared with patients with medium and low SPP1 expression." (PMID 29957058, 2019). "Our independent analyses of OPN gene expression, encoded by SPP1, demonstrate a strong negative correlation between OPN expression levels and the survival of patients with colon adenocarcinoma and rectum adenocarcinoma." (PMID 29957058, 2019).
coronary atherosclerosis (7 papers, 2016 to 2024). Atherosclerosis of the coronary vasculature. "Therefore, SPP1+ macrophages in coronary PVAT may participate in the progression of coronary atherosclerosis." (PMID 37706320, 2023).
epilepsy (7 papers, 2018 to 2024). A brain disorder characterized by episodes of abnormally increased neuronal discharge resulting in transient episodes of sensory or motor neurological dysfunction, or psychic dysfunction. "There were 8 DEGs (Ldoc1, Nefh, Parm1, Ptpro, Pvalb, Spp1, Synpr, Vamp1) shared by the schizophrenia and epilepsy gene sets, suggesting a common molecular basis between the two disorders." (PMID 37545878, 2023). "However, the exact role of Spp1 following epilepsy requires further evaluation." (PMID 29925434, 2018). "The scRNA‐seq of non‐affected brain areas of patients with epilepsy revealed 10 distinct microglial clusters, with the genes CCL2, CCL4, and SPP1 being involved." (PMID 38572804, 2024). "At several epilepsy-related genes, like HDAC11, SPP1, GAL, DRD1 and SV2C, significant differential methylation and differential gene expression coincided." (PMID 31887157, 2019).
myocarditis (7 papers, 2015 to 2025). Myocarditis is a condition that is characterized by inflammation of the heart muscle (myocardium). "Conversely, it is in agreement with what has been observed in animal models, in which an overexpression of Spp1 causes myocarditis and myocardial dilation." (PMID 34451895, 2021). "A comparative analysis of cellular proportions demonstrated a significant expansion of Spp1+ macrophages in mice with acute myocarditis." (PMID 41222876, 2025). "Collectively, these findings demonstrate that STAT4 drives Spp1 expression in acute myocarditis, highlighting its potential as a therapeutic target for this condition." (PMID 41222876, 2025). "RNA-seq analysis identified Spp1, Lipg, and Acod1 among the most significantly and consistently upregulated genes across all myocarditis models, as defined by their high fold-change and statistical significance." (PMID 41222876, 2025). "GO analysis indicated that Spp1+ macrophage could regulate inflammatory response and leukocyte migration, implying that Spp1+ macrophages execute distinct function in acute myocarditis." (PMID 41222876, 2025).
nasopharyngeal carcinoma (7 papers, 2014 to 2024). A carcinoma arising from the nasopharyngeal epithelium. "SPP1 plays an essential role in maintaining macrophage M2 polarization, and ISG15 is associated with poor prognosis in patients with nasopharyngeal carcinoma and induces a macrophage M2-like phenotype." (PMID 36551288, 2022).
oral squamous cell carcinoma (7 papers, 2013 to 2024). "However, we observed that higher expression of Jun or CCND1 or SPP1 was associated with short survival of oral squamous cell carcinoma patients." (PMID 30459815, 2018). "Studies have found that there are differences in the expression of TGFB1, SPP1 and other genes in oral squamous cell carcinoma (OSCC)." (PMID 31485443, 2019).
periodontitis (7 papers, 2018 to 2025). An acute or chronic inflammatory process that affects the tissues that surround and support the teeth. "In the Pg sample, we observed interactions between ADM and CALCRL, which is related to periodontitis; EDA and EDA2R, which is related to ectodermal development; and SPP1 and CD44 and SPP1 and (ITGA4+ITGB1), which promotes phosphoprotein secretion and regulates bone salinization." (PMID 37287452, 2023).
preeclampsia (7 papers, 2008 to 2025). Preeclampsia is a hypertensive disorder of pregnancy that is characterized by new-onset hypertension with proteinuria presenting after 20 weeks of gestation, and depending on mild or severe forms may initially present with severe headache, visual disturbances, and hyperreflexia. "qRT-PCR confirmed LEP and CRH increased, while SPP1 expression in preeclampsia samples." (PMID 39967661, 2025). "Indeed, a number of genes regulated in this array were previously found to be associated with pregnancy complications such as preeclampsia (MR, CCL2, IGF-1, secreted phosphoprotein (SPP)-1, MMP-9), preterm labour (CCL18) and intrauterine growth restriction (IGF-1)." (PMID 18446208, 2008). "Our research showed that SPP1, Annexin, MIF, Visfatin, VEGF, Galectin, PTN, and CCL signalings were significantly inhibited among the three subtypes of macrophages in the preeclampsia group." (PMID 40216654, 2025).
pulmonary TB (7 papers, 2016 to 2026). "To further confirm the presence of SPP1+ macrophages in human lung TB granulomas, we performed immunohistochemical staining of tissues from two independent donors." (PMID 41489684, 2026).
small cell lung carcinoma (7 papers, 2015 to 2022). Small cell lung cancer (SCLC) is a highly aggressive malignant neoplasm, accounting for 10-15% of lung cancer cases, characterized byrapid growth, and early metastasis. "In SCLC (small-cell lung cancer) patients, SPP1 is one of the most upregulated genes to stimulate epithelial–mesenchymal transition (EMT)." (PMID 35453667, 2022). "For example, by inhibiting autophagy and apoptosis, SPP1 promotes the development of small cell lung cancer." (PMID 33968738, 2021).
aortic aneurysm (6 papers, 2014 to 2025). A ruptured aneurysm located in the wall of the proximal portion of the descending aorta proceeding from the arch of the aorta. "SPP1 signaling mainly sent from macrophages and became much more abundant in the aortic aneurysm group in both organisms, although hTREM2 Mφ in the normal group showed strong SPP1 signaling." (PMID 36703732, 2022). "MIF and SPP1 signaling networks participated in aortic aneurysm in both organisms." (PMID 36703732, 2022). "We identified a subpopulation of the Trem2 macrophage featured biological function on macrophage migration and expression of SPP1, TREM2, FABP5, and ANXA2 in both organisms during the pathology of aortic aneurysm." (PMID 36703732, 2022).
bone tumor (6 papers, 2006 to 2024). "OPN, also known as SPP1 (secreted phosphoprotein, is a secreted and chemokine-like glyco-phosphoprotein involved in the early phases of osteoblast differentiation and in other physiological and pathological processes, such as ECM mineralization, bone resorption, and bone tumor progression." (PMID 32796668, 2020).
brain tumors (6 papers, 2015 to 2021). "In BrM, Spp1/SPP1 was found highly expressed or upregulated in both TAM populations across species, however with slightly higher expression levels in TAM-MG, similar as in primary brain tumors." (PMID 34539650, 2021).
carotid atherosclerosis (6 papers, 2016 to 2024). A thickening and loss of elasticity of the walls of carotid arteries that occur with formation of atherosclerotic plaques. "Additionally, MYH11, KLF5, and SPP1 expression patterns were found to be associated with symptomatology of human carotid atherosclerosis." (PMID 29562638, 2018).
cervical squamous cell carcinoma (6 papers, 2020 to 2024). A squamous cell carcinoma arising from the cervical epithelium. "Moreover, Chi-square test identified tumor stage, HPV type, and tumor size were positively correlated with SPP1 expression, while tumor size and numbers of positive nodes were related to CD44 expression in CC patients from The Cancer Genome Atlas cervical squamous cell carcinoma (TCGA-CESC)." (PMID 38346944, 2024).
colorectal tumor (6 papers, 2017 to 2023). "Expression of SPP1 was enriched in colorectal tumor tissues compared to matched PBMC and healthy colon." (PMID 33670921, 2021). "Moreover, a significantly high correlation (R = 0.23, p < 0.001) was identified between the signature enrichment of CAFEndMT and SPP1+ TAMs in the spatial transcriptomic profile from seven colorectal tumor samples." (PMID 36333338, 2022). "Elevation of SPP1 expression was globalized across myeloid cell states, with all sub-clusters showing increased SPP1 levels in colorectal tumor relative to normal colon, suggesting that tumor residency is sufficient for inducing SPP1 expression across the myeloid lineage." (PMID 33670921, 2021).
mastitis (6 papers, 2009 to 2025). Inflammation of breast tissue during lactation or postpartum due to an obstructed duct or infection. "This suggests a significant association between SPP1 gene polymorphisms and recessive mastitis in dairy cows, aligning with the findings of the present study." (PMID 40428307, 2025). "The genes NOD2, CXCR1, SPP1 and LF, which are implicated in resistance to occult mastitis, were genotyped utilizing the efficient and cost-effective Kompetitive Allele-Specific PCR (KASP) technology." (PMID 40428307, 2025). "Because of the potential immunological role of SPP1 in the milk of cows diagnosed with mastitis, the next step was the validation of SPP1 genetic variants that would explain the SCS observed in the dairy population." (PMID 19765294, 2009). "This study reports the link between DNA polymorphisms of SPP1, the number of milk immune cells and, potentially, the susceptibility to mastitis." (PMID 19765294, 2009). "This study reports the link between DNA polymorphisms within the innate immune SPP1 gene, the number of milk immune cells and, potentially, susceptibility to mastitis." (PMID 19765294, 2009). "We thus found polymorphisms in the genomic sequence of SPP1 that influence the number of somatic cells in milk and, potentially, influence their susceptibility to mastitis, although this latter assumption remains to be validated." (PMID 19765294, 2009). "Identifying favourable SPP1 alleles for mastitis resistance would make it possible for dairy breeders to increase them in the Canadian Holstein population to potentially increase the natural resistance to mammary gland infection." (PMID 19765294, 2009). "A variation at SPP1 was reported to regulate milk protein gene expression, mastitis resistance and lactation persistency in dairy cows." (PMID 32708940, 2020). "Following the detection of this key gene in the mammary somatic cells isolated early during the immune response, we evaluated the association of SPP1 with SCC, which is the most widely used indicator of mastitis." (PMID 19765294, 2009).
parasite infection (6 papers, 2009 to 2024). "In addition to strong expression of IFNβ and CCL5 in all cell types, parasite infection induces the expression of genes involved in cell-matrix interactions (osteopontin; SPP1) carbohydrate modification (B4GT5 and B3GNT2), vesicular transport SYTL3 and T-SNARE1 and Ca2+ homeostasis STIM1 and CARKL." (PMID 19480704, 2009).
postmenopausal osteoporosis (6 papers, 2021 to 2025). Metabolic disorder associated with fractures of the femoral neck, vertebrae, and distal forearm. "Notably, the hub gene SPP1 (osteopontin) identified here is also implicated in postmenopausal osteoporosis, suggesting shared pathways between metabolic and skeletal disorders." (PMID 40725440, 2025). "Previous clinical studies have also shown that SPP1 is involved in bone strength and remodelling, suggesting that serum SPP1 positively correlates with lower BMD and that high circulating SPP1 levels could be targeted as a biomarker for early diagnosis of postmenopausal osteoporosis." (PMID 39919333, 2025).
rectal cancer (6 papers, 2017 to 2024). A primary or metastatic malignant neoplasm that affects the rectum. "High protein expression of SPARC and SPP1 was associated with shorter recurrence-free survival (RFS) and PFS, respectively, in patients with rectal cancer (respectively)." (PMID 36895491, 2023). "Using digital quantification, we performed IHC analysis of S100A4, SPP1 and SPARC in human colon and rectal cancer tissue." (PMID 36895491, 2023). "We for the first time performed complex analysis of S100A4, SPP1 and SPARC mRNA levels in terms of survival rates in common CRC groups and in patients with colon and rectal cancer separately." (PMID 36895491, 2023).
schizophrenia (6 papers, 2019 to 2025). A major psychotic disorder characterized by abnormalities in the perception or expression of reality. "In particular, the novel interaction between Mitohigh_Neuron subsets and endothelial cells, established through SPP1 signaling, may be a potential molecular mechanism pathway in schizophrenia.(2(Our analysis also highlights the role of mitophagy in immune cells." (PMID 39355378, 2024).
scoliosis (6 papers, 2009 to 2025). A congenital or acquired spinal deformity characterized by lateral curvature of the spine. "Idiopathic scoliosis cells had a 2-fold overexpression of SPP1 compared to controls but treated cells showed a 2.7-fold decrease in expression." (PMID 28290481, 2017).
thyroid tumor (6 papers, 2010 to 2022). A benign or malignant neoplasm affecting the thyroid gland. "Interestingly, the ligands PLAU and SPP1 have previously been associated with invasion and progression in several types of solid tumors, and both in vivo and in vitro models have demonstrated overexpression of these ligands in thyroid tumors." (PMID 20877637, 2010). "Some internal validations emerged, such as the pairs PLAU/PLAUR, SPP1/CD44, and SPP1/ITGA9, whose ligands have been demonstrated overexpressed in thyroid tumors as well as in our in vitro model." (PMID 20877637, 2010).
amyloid (5 papers, 2021 to 2025). "In APPNL−F mice, SPP1-driven upregulation of C1qa in microglia led to enhanced synaptic engulfment, while genetic ablation of Spp1 prevented synapse loss despite ongoing amyloid deposition." (PMID 41398960, 2025). "Recently, perivascular macrophage expression of Spp1 was shown to be necessary for microglial engulfment of synapses and upregulation of phagocytic markers in the mouse hippocampus with amyloid pathology." (PMID 36945656, 2023). "Secreted phosphoprotein 1 (SPP1) produced predominantly by perivascular macrophages has been shown to drive microglial phagocytosis of synapses, thereby contributing to the development of amyloid-induced neurodegeneration." (PMID 37799623, 2023).
calcific aortic valve disease (5 papers, 2011 to 2024). "Despite our data suggesting that reduced Sox9 function promotes matrix mineralization via relieved repression of Spp1, Osteopontin and Sox9 are both highly expressed in human valves excised from patients with end-stage calcific aortic valve disease." (PMID 22046352, 2011). "The expression of SPP1, TNC, SCG2, FAM20A, and CD52 was all significantly up-regulated in calcific aortic valve disease." (PMID 34020624, 2021). "Compared with those in the normal group, SPP1 is positively correlated with dendritic cells (DCs) and regulatory T cells in the calcific aortic valve disease (CAVD), but there is a negative correlation between SPP1 and M2 phenotype macrophage." (PMID 38919629, 2024).
chronic heart failure (5 papers, 2011 to 2022). "An excess of SPP1 was associated with left-ventricular stiffness and systolic dysfunction in patients with chronic heart failure and hypertensive heart disease." (PMID 35347083, 2022).
clear cell renal cell carcinoma (5 papers, 2015 to 2025). "The immunosuppressive role observed in clear cell renal cell carcinoma further supports the notion that SPP1+ TAMs may act as specialised effectors within the broader immunosuppressive TAM pool." (PMID 40395129, 2025). "Similarly, in clear cell renal cell carcinoma, SPP1+ TAMs exhibit an M2‐like signature, characterised by high expression of CXCL9, CXCL10, and the pan‐macrophage marker CD68." (PMID 40395129, 2025).
diffuse large B-cell lymphoma (5 papers, 2016 to 2024). "In a recent study, increased SPP1 expression was detected in diffuse large B-cell lymphoma by tissue microarray analysis, particularly in patients with reduced overall survival." (PMID 33562105, 2021).
disc degeneration (5 papers, 2018 to 2025). "By establishing a rat tail intervertebral disc needle-puncture model to simulate disc degeneration and employing immunohistochemical staining techniques, we confirmed significant upregulation of SPP1 expression in degenerated discs." (PMID 41357134, 2025). "SPP1 is involved in the pathogenesis of disc degeneration and may be a new target for intervention in IVDD." (PMID 41357134, 2025). "Therefore, we do not recommend secondary viral injection in IVDD animals to explore therapeutic effects of SPP1 or ITGa5 knockdown, which is contrary to our intention to explore therapeutic strategies for disc degeneration." (PMID 39721032, 2025). "It is speculated that SPP1/OPN may be a marker for the severity of disc degeneration." (PMID 34611583, 2021). "They therefore assumed that SPP1/OPN might mark the severity of disc degeneration." (PMID 30115120, 2018). "This suggests that SPP1 accumulates in NP tissues of patients with IVDD and may be responsible for disc degeneration." (PMID 41357134, 2025).
glomerulosclerosis (5 papers, 2010 to 2022). A hardening of the kidney glomerulus caused by scarring of the blood vessels. "Together, our data suggest that early M1 macrophage infiltration may be involved in the rupture of BC and that SPP1-mediated M2 macrophage polarization may contribute to glomerulosclerosis and crescent fibrosis." (PMID 35309370, 2022).
nephrocalcinosis (5 papers, 2019 to 2026). Nephrocalcinosis is a disorder that occurs when too much calcium is deposited in the kidneys. "We speculate that evaluating this model at an older age or in the setting of high dietary phosphate consumption could elicit a significant nephrocalcinosis phenotype in the pcy/pcy; Spp1−/− mice." (PMID 39238069, 2024).
retinal degeneration (5 papers, 2014 to 2024). Degeneration of the retina. "In the human eye SPP1 is distributed in the aqueous humor (AqH) and the vitreous fluid and reported to mediate photoreceptor survival in experimental models for retinal degeneration." (PMID 33042148, 2020).
acute lung injury (4 papers, 2019 to 2023). A condition of lung damage that is characterized by bilateral pulmonary infiltrates (pulmonary edema) rich in neutrophils, and in the absence of clinical heart failure. "A recent study demonstrated that Spp1 serum levels were correlated with kidney injury, and facilitated with AKI–induced acute lung injury (ALI)." (PMID 36932340, 2023).
acute respiratory distress syndrome (4 papers, 2021 to 2025). Progressive and life-threatening pulmonary distress in the absence of an underlying pulmonary condition, usually following major trauma or surgery. "SPP1 is known to be highly expressed in alveolar macrophages from patients with acute respiratory distress syndrome (ARDS) and mice that received intratracheal instillation of LPS." (PMID 40559389, 2025).
CNS lymphoma (4 papers, 2016 to 2025). "Therefore, in the DLBCL-related malignancy primary central nervous system lymphoma (PCNSL), SPP1 may act in a paracrine mode but may share downstream activities as described for HL in this study." (PMID 40149711, 2025).